MEN1 (menin 1)
Diseases named in the same sentence as MEN1 in open-access papers (continued):
Sharing a sentence is not in itself a finding about the gene and the disease.
Hypercalcemia (28 papers, 2009 to 2025). An abnormally increased calcium concentration in the blood. "It is reported that the postoperative persistent PHPT and hypercalcemia in patients with MEN1-related PHPT are significantly linked with anxiety, depression, fatigue, and decreased social function, all deleterious to the quality of life." (PMID 37795364, 2023). "Patients with MEN1-associated PHPT had more severe hypercalcemia compared to those with a sporadic pathology and were distinguished with multiple concomitant endocrine lesions." (PMID 37465121, 2023). "For instance, gastroesophageal reflux may be related to the hypercalcemia-associated direct effects or to MEN1 components, but, also, acute lumbar pain with abdominal spreading may be caused by the presence of kidney and ureteral stones." (PMID 38928056, 2024). "What is the diagnostic value of early onset of hypercalcemia in MEN1?" (PMID 30065698, 2018). "As he had previously been diagnosed with and treated for relatively young onset diabetes and multiple urinary tract stones associated with hypercalcemia, it is highly likely that MEN1 could have been diagnosed and treated earlier had detailed systemic examinations been performed at that time." (PMID 38200366, 2024). "MEN1-related PHPT accounts for approximately 2% to 4% of all cases of PHPT, and it is estimated that the majority of MEN1 patients will develop hypercalcemia by the time they turn 50 years old." (PMID 40177730, 2025). "In summary, this case emphasizes the importance of considering MEN1 in patients with refractory or recurrent GI ulceration, particularly in the presence of hypercalcemia or pancreatic lesions." (PMID 41541958, 2025). "Only after repeated admissions, elevated fasting gastrin levels, and biochemical evidence of hypercalcemia with raised parathyroid hormone (PTH) was MEN1 suspected and subsequently confirmed on genetic testing." (PMID 41541958, 2025). "In most cases, mPHPT can remain asymptomatic for a long time, but mild to moderate progression to hypercalcaemia typically begins in adolescence, and almost all MEN1 patients are expected to have hypercalcemia by the age of 50." (PMID 39518523, 2024). "The current MEN1 guidelines focus primarily on correcting hypercalcemia, both immediately (avoid persistent disease) and in the long term (avoid recurrent disease)." (PMID 27402205, 2016). "There are three goals for parathyroidectomy in MEN1 patients: correct hypercalcemia, avoid permanent hypoparathyroidism, and facilitate potential future operation." (PMID 27402205, 2016). "The hypercalcemia of FIHP, MEN1, MEN2, and HPT-JT is associated with hypercalciuria and sometimes kidney stones, whereas that of FBHH is associated with a low urinary calcium–creatinine clearance ratio (< 0.01)." (PMID 18446382, 2009). "However, it can be challenging because of asynchronous multiglandular involvement, related to higher rates of recurrent hypercalcemia (approximately 20%-60% of MEN1 patients, compared to only 4% sporadic PHPT patients)." (PMID 40177730, 2025). "Some patients with non-syndromic PHPT may have mutations of the MEN1 gene or the calcium-sensing receptor (CASR), whose loss of function mutations usually cause FHH1, a disorder associated with mild hypercalcemia and may follow a benign clinical course." (PMID 38038882, 2024). "Additionally, in accordance with other registries, primary manifestations of MEN1-related PHPT were biochemically diagnosed as hypercalcemia and nephrolithiasis." (PMID 35407574, 2022). "In MEN1 patients, PTX is strongly suggested in the presence of increased PTH and hypercalcemia to prevent/reduce the early-onset bone mass loss and grant, in young patients, the achievement of the bone mass peak; routine monitoring of bone metabolism and bone mass should start from adolescence." (PMID 34440663, 2021).
Hypercalcemia (continued). "Genetic testing for mutations in the CDC73 (HRPT2) gene was negative; MEN‐1 mutations were not evaluated due to the absence of evidence of other associated tumors or familial history of hypercalcemia or MEN‐1‐associated tumors." (PMID 32884778, 2020). "In patients affected by genetic syndromes as HPT-JT and MEN1, recurrent hypercalcemia following initial surgery may be a sign of recurrence of the primary tumour and/or distant metastases, metastases or disease in a further PT." (PMID 31142320, 2019). "The time interval—probably variable and multifactorial—between occurrence of the second mutational event in a tumor precursor parathyroid cell and the onset of hypercalcemia is unknown in MEN1." (PMID 30065698, 2018). "Thus, the age at the diagnosis of hypercalcemia is one of the important clues for diagnosis of MEN1." (PMID 30065698, 2018). "Thus, MEN1 becomes more relevant in the differential diagnosis of hypercalcemia after the age of 8 years." (PMID 30065698, 2018). "This case highlights the diagnostic complexity of MEN1 in the absence of a family history, in which gastrointestinal ulcerations with bleeding, fleeting thrombophlebitis, and hypercalcemia may serve as early clinical clues." (PMID 41541958, 2025). "Thus, hypercalcemia seems to be rare in MEN1 for this age group." (PMID 30065698, 2018). "Hereditary disorders associated with hypercalcemia include familial isolated primary hyperparathyroidism (FIHP), familial benign hypocalciuric hypercalcemia (FBHH), multiple endocrine neoplasia type 1 (MEN1), MEN type 2 (MEN2), and the hyperparathyroidism–jaw tumor (HPT-JT) syndrome." (PMID 18446382, 2009). "In most cases, MEN1 PHPT can remain asymptomatic for a long period, but mild-moderate hypercalcemia typically starts during adolescence, and almost all MEN1 patients are expected to have hypercalcemia by the age of 50." (PMID 34440663, 2021). "Indications for parathyroidectomy in patients with MEN1 are similar to those for individuals with sporadic PHPT and include symptomatic or marked hypercalcemia/hypercalciuria, nephrolithiasis, and/or evidence of bone disease." (PMID 31263451, 2019). "However, since MEN4 presents a clinical phenotype overlapping that of MEN1, it is highly probable that PHPT-related hypercalcemia can alter bone metabolism and reduce BMD value the same way we find in MEN1 patients." (PMID 32326947, 2020). "Therefore, in the case of MEN1-related tumors, urolithiasis, or cholelithiasis without hypercalcemia, should raise a suspicion of PHPT and lead to further investigation." (PMID 33807230, 2021). "However, hypercalcemia has been rarely reported during the first decade in MEN1 with no more than 16 cases reported in the two large MEN1 series." (PMID 30065698, 2018).
lipoma (24 papers, 2010 to 2026). A benign, usually painless, well-circumscribed lipomatous tumor composed of adipose tissue. "Biopsies of facial angiofibromas, lipomas, and collagenomas from patients harboring germline MEN1 variants exhibited an allelic deletion of chromosome 11 including the MEN1 locus." (PMID 37484956, 2023). "Of interest, in one familial MEN1 mutation-positive index case, the histologic examination of an apparently resected benign lipoma was consistent with the diagnosis of liposarcoma." (PMID 37484956, 2023). "In our study, 46% of patients of the whole series, including relatives carrying MEN1 mutation, had at least one cutaneous lesion, lipoma, and/or hibernoma." (PMID 37484956, 2023). "The prevalence of lipomas was also significantly higher in F-MEN1 than in S-MEN1 (p = 0.009) and in MEN1 mutation-positive than in MEN1 mutation-negative (p = 0.01) index cases." (PMID 37484956, 2023). "High quality evidence supports a direct association between pathogenic MEN1 variants and neoplasms of the skin (angiofibromas and collagenomas), adipose tissue (lipomas and hibernomas), and smooth muscle (leiomyomas)." (PMID 36325452, 2022). "Lipomas can also be found in association with genetic syndromes including MEN1, Birt-Hogg-Dubé, and Cowden Syndrome." (PMID 36428828, 2022). "These patients carry a heterozygous germline mutation in MEN1, and loss of the remaining normal copy of MEN1 has been documented in such MEN1-associated lipomas." (PMID 26229531, 2015). "Our data highlight the potential of two different in vitro experimental systems to study MEN1-associated lipoma biology and to investigate the mechanisms that govern fat-cell size, proliferation, and function." (PMID 26229531, 2015). "Multiple endocrine neoplasia type 1, related to a MEN1 gene mutation, is often associated with lipomas and sometimes hibernomas (lipoma of brown adipose tissue), epidural lipomatosis, and familial angiolipomatosis, for which the prevalence is unknown." (PMID 33800991, 2021). "Therefore, there is a dearth of molecular studies exploring the pathogenesis of MEN1-associated lipoma." (PMID 26229531, 2015). "Patients with MEN1 frequently develop cutaneous tumors, including lipomas, collagenomas, and fibrovascular facial tumors." (PMID 41155355, 2025). "Sporadic MEN1 cohort (n = 55): Sixteen (29%) patients had at least one cutaneous lesion and/or lipoma." (PMID 37484956, 2023). "Familial MEN1 cohort (n = 129): Sixty-nine (53%) patients had at least one cutaneous lesion, lipoma, and/or hibernoma." (PMID 37484956, 2023). "The presence of lipomas in patients with MEN1 has been reported since the first description of the syndrome." (PMID 37484956, 2023). "Lipomas from MEN1 patients have been shown in multiple reports to have LOH at the MEN1 locus, consistent with a causal relationship with MEN1, and there are no clear genotype-phenotype correlations." (PMID 36325452, 2022). "Lipomas can also be the first clinical manifestation in MEN1 patients, diagnosed as young as 9 years, but there is not a clear correlation with patient age or disease duration." (PMID 36325452, 2022). "The most common cutaneous tumors found in patients with MEN1 were angiofibromas, collagenomas, and lipomas." (PMID 36428828, 2022). "Several possible criteria for identifying patients with MEN1, based on the presence of angiofibromas, collagenomas, lipomas, and combinations, were analyzed." (PMID 36428828, 2022). "In summary, lipomas are clearly established as an MEN1 clinical manifestation, occurring in up to one third of patients." (PMID 36325452, 2022). "Angiofibromas are the most frequent cutaneous tumors in patients with MEN1, followed by collagenoma and lipoma." (PMID 36428828, 2022). "Other skin tumors found in MEN1 patients were lipomas, basal cell carcinoma, melanoma, and acrochordons." (PMID 36428828, 2022).
lipoma (continued). "MEN1 patients can also develop lipomas, collagenomas, facial angiofibromas, CNS tumors including meningiomas and ependymomas, and smooth-muscle tumors, including leiomyomas." (PMID 33312161, 2020). "The availability of lipoma specimens from human MEN1 patients or from the mouse models of MEN1 and the availability of normal cells matched to lipoma are a challenge in the study of MEN1-associated lipoma." (PMID 26229531, 2015). "Lipoma in patients with MEN1 occurs as an overgrowth of fat tissue, frequently multiple, and usually in the subcutaneous area of the back, neck, shoulder, arm, thigh, or abdomen." (PMID 26229531, 2015). "Other less specific clinical elements include MEN1-related cutaneous tumours such as lipomas, angiofibromas, and collagenomas that have been found with a higher rate than general population and uncommon neoplasia like leiomyomas and breast and ovarian tumours, as well as T-cell lymphoma." (PMID 40364143, 2025). "We found a significantly higher prevalence of angiofibromas and lipomas in F-MEN1 compared with S-MEN1 and in MEN1 mutation-positive compared toMEN1mutation-negative patients." (PMID 37484956, 2023). "We found a significantly higher prevalence of lipomas in MEN1 mutation-positive compared to MEN1 mutation-negative (p = 0.01) and in familial compared to sporadic (p = 0.009) cohorts if only index cases were considered." (PMID 37484956, 2023). "In the index cases cohort, we observed a significantly higher prevalence of angiofibromas (OR = 3.7, p = 0.02) and lipomas (OR = 3.0, p = 0.01) in the MEN1 mutation-positive compared to MEN1 mutation-negative index cases." (PMID 37484956, 2023). "In the whole cohort, the prevalence of lipomas was significantly higher in MEN1 mutation-positive compared to MEN1 mutation-negative patients (OR = 2.7, p = 0.02) and in F-MEN1 than in S-MEN1 (p = 0.03), only after adjustment for age." (PMID 37484956, 2023). "In patients presenting with one major endocrine manifestation of MEN1, the presence of cutaneous lesions, i.e., angiofibromas and lipomas, might suggest the diagnosis of MEN1 and a possible indication of genetic screening." (PMID 37484956, 2023). "Frequency and distribution of angiofibromas and lipomas in familial and sporadic MEN1 patients." (PMID 37484956, 2023). "The most common cutaneous tumors found in MEN1 are angiofibromas, collagenomas, and lipomas." (PMID 36428828, 2022). "In the literature, lipomas are reported to be found in 0.9-34% of MEN1 patients." (PMID 36325452, 2022). "The penetrance by age 40 of lipomas in MEN1 patients has previously been estimated to 30%." (PMID 36325452, 2022). "Lipomas can grow quite large and may need to be resected due to symptoms or for cosmetic reasons, but around 70% of MEN1 patients with lipomas can be managed conservatively." (PMID 36325452, 2022). "MEN1 mutations have not previously been reported in sarcomas and have been described only occasionally in benign smooth muscle tumors and rarely in lipomas." (PMID 30889380, 2019). "Cutaneous manifestations are common in MEN1 and may include lipomas, angiofibromas, and collagenomas, with the penetrance of these lesions by age 40 being 30, 85, and 70%, respectively." (PMID 31263451, 2019). "Lipomas were the first clinical manifestation of MEN1 in 7 cases (4.83% of affected patients) with a mean age of onset of 21.9 + 11.5 years (range 9–39 years); 3 were index cases (mean age 33.7 + 6.2 years; range 25–39 years) and 4 were relatives (mean age 13.0 + 4.3 years; range 9–20 years)." (PMID 30428914, 2018). "Furthermore, endocrine-inactive tumors, such as lipomas, angiofibromas and collagenomas are frequently identified in MEN1 patients." (PMID 25663877, 2015). "Further studies of these benign fatty lesions could provide insights into the pathogenesis of MEN1-related lipomas and the growth of normal fat tissue." (PMID 26229531, 2015).
lipoma (continued). "Therefore, the effect from menin loss on the expression of prolactin gene family is not relevant in the context of MEN1-associated human lipoma." (PMID 26229531, 2015). "The MEN1-associated lipoma is a type of benign fat-cell tumor occurring in about 30% of MEN1 patients and similar to the other MEN1-associated endocrine and nonendocrine tumors has biallelic inactivation of MEN1 (1st hit in the germline, 2nd hit tissue-specific)." (PMID 26229531, 2015). "Several non-endocrine manifestations such as lipomas, angiofibromas, collagenomas, hibernomas, leiomyomas, and central nervous system tumors (meningiomas and ependymomas) have been reported in MEN1 patients." (PMID 37484956, 2023). "Despite the presence of three different dermatologic tumors, the patient did not present more common MEN1 cutaneous manifestations such as angiofibroma, collagenoma, or lipoma." (PMID 36428828, 2022). "Because sporadic lipomas are not uncommon in the general population, the finding of a lipoma in a patient suspected to have MEN1 is not sensitive enough to make the diagnosis." (PMID 36325452, 2022). "Facial angiofibromas, collagenomas, lipomas, and meningiomas have been shown to occur frequently in MEN1 patients compared to the other non-endocrine tumors." (PMID 31527438, 2019). "Shortly after the identification of the MEN1 gene, several nonendocrine tumours were also reported in MEN1 patients, such as lipoma and angioma." (PMID 20663219, 2010). "Lipomas in MEN1 patients are not infrequently multiple and are typically subcutaneous, but they can also be found more deeply and reach large sizes that may require surgical extirpation." (PMID 36325452, 2022).
leukemia (22 papers, 2016 to 2026). A malignant (clonal) hematologic disorder, involving hematopoietic stem cells and characterized by the presence of primitive or atypical myeloid or lymphoid cells in the bone marrow and the blood. "Recently a novel menin inhibitor, bleximenib, showed efficacy in cell lines of KMT2A-r leukemia harboring the menin mutations (MEN1-M327I or MEN1-T349M)." (PMID 41310838, 2025). "Revumenib induces remission in 30% of relapsed/refractory leukemia patients, although mutations in MEN1 can lead to drug resistance." (PMID 38601080, 2024). "Furthermore, GSEA revealed that a set of genes that we had previously found to be downregulated upon loss of Kmt2a in MN1-driven leukemia was enriched in Men1−/− versus Men1wt MN1-driven AML cells." (PMID 33542482, 2021). "This is in line with the reported high selectivity of VTP50469 and other MEN1 inhibitors, including MI-3454, towards MLLr leukemia." (PMID 38003662, 2023). "Surprisingly, a dependency on MEN1 was revealed not only in MLLr-, NPM1m-, or MN1m-driven leukemia, but also in other types of neoplasms (Ewing sarcoma, breast cancer, and castration-resistant prostate cancer), which were driven by alternative mutations." (PMID 38003662, 2023). "Comparing AML and B-ALL, two leukemia types often driven by MLLr, MEN1 dependency correlated with the presence of MLLr only in AML." (PMID 38003662, 2023). "Previous analyses of genome-wide loss-of-function screening datasets of the Achilles project revealed the highest dependency on MEN1 in “multiple myeloma”, followed by “leukemia” categories." (PMID 38003662, 2023). "We established in vivo MN1-driven leukemia on a conditional Men1f/f background and utilized retroviral expression of Cre-recombinase (MSCV-Cre-tdTomato) to excise Men1 alleles." (PMID 33542482, 2021). "The strong overlap between genes downregulated upon inactivation of Kmt2a and inactivation of Men1 supports that the effect of Menin/Kmt2a inhibition in MN1-driven leukemias is a result of disrupting the Kmt2a complex." (PMID 33542482, 2021). "Genetic inactivation of Men1 led to a decrease in the number of functional leukemia-initiating cells." (PMID 33542482, 2021). "Inhibitors targeting MEN1-MLL have been shown to reverse HOXA and MEIS gene expression, thereby releasing the differentiation block associated with MLL-rearranged leukemia." (PMID 31552175, 2019). "The association of MEN1 or LEDGF with MLL is required for chromatin localization of the complex and transcription of their target genes, which are crucial for MLLr-leukemias development." (PMID 29692408, 2018). "Resistance to menin inhibitors in KMT2Ar leukemias often arises from epigenetic mechanisms and alternative cellular pathways rather than solely genetic mutations in the MEN1 gene." (PMID 39682203, 2024). "We conclude that the role of MEN1 in leukemia is not limited to its interaction with KMT2A, hence pharmacological degradation may be a better approach than the inhibition of individual MEN1 PPIs." (PMID 38003662, 2023). "Advances in treating MLL-rearranged leukemia were also achieved by using small molecules to block the KMT2A binding site on Menin, a protein encoded by MEN1 and required for oncogenic transformation, leading to the inhibition of the aberrant leukemogenic transcription program." (PMID 35328068, 2022). "In this study we report that targeting MEN1 gene-encoded protein menin, known as an important DOT1L cofactor in MLL-rearranged leukaemia and antiestrogen therapy-resistant breast cancer cells may represent an effective therapeutic approach against OC." (PMID 36333801, 2022). "Furthermore, our data support previous results generated after MEN1 knock-out in the Project Achilles data where multiple myeloma and leukemia cells were found to be the most sensitive." (PMID 31947537, 2020).